IL1B (interleukin 1 beta)
Diseases named in the same sentence as IL1B in open-access papers (continued):
Sharing a sentence is not in itself a finding about the gene and the disease.
infection (continued). "While no change in IFNα or IFNβ expression in HIV-1 infected KCs was observed, IL-1β mRNA and both intracellular and secreted IL-1β was increased by HIV-1BaL infection." (PMID 32612603, 2020). "It is well known that C. acnes induces the release of proinflammatory cytokines and chemokines, including IL-1β, IL-6, interferon (IFN)-γ, TNF-α, and IL-8 at the onset of infection." (PMID 32867396, 2020). "At 3 h post infection, both viable and heat-killed APEC strongly up-regulated gene expression of pro-inflammatory cytokines IL-1β and IL-6, chemokine IL-8 and the anti-inflammatory cytokine IL-10 compared to control cells that were mock-treated with medium." (PMID 32972448, 2020). "Serum levels of pro-inflammatory cytokines were similar among the participants with different infection status (TNF-α; p = 0.290, IL-1β; p = 0.442, IL-6; p = 0.686, IFN-γ; p = 0.801, IL-8; p = 0.546, IL-12; p = 0.154)." (PMID 33317454, 2020). "For instance, chickens that were infected with genotype VIII NDV were reported to express significantly higher levels of IL-1β, IFN-γ, and IL-12α on the third day of infection than chickens that were infected with the genotype VII strain." (PMID 32293543, 2020). "In contrast, IL-1β, IFN-γ, IL-22, IL-10, IL-27 and IL-35 were present in lower levels in the lungs of these mice at all post-infection periods assessed." (PMID 32647342, 2020). "Specifically, attenuation in the ΔcomR group was the most obvious as the concentrations of TNF-a, IL-1β, and MCP-1 were all significantly reduced at 3, 6, and 9 h post-infection." (PMID 32825733, 2020). "At 1 week post-infection, when T. gondii infection is systemic, mice had elevated circulating IFN-γ, IL-1β, IL-6, and TNF-α compared to uninfected controls (grey background)." (PMID 32973293, 2020). "Specifically, the IL-1β gene levels in the DF1 cells increased gradually following GM infection, reaching a final peak (148.5-fold) at 36 h post-infection (hpi)." (PMID 32293543, 2020). "Addition of LL-37 to the mammary epithelium stimulated transcriptional expression of IL-1β and TNF-α at a later point (8 h post-infection) (p < 0.05)." (PMID 32117805, 2020). "In our study, we observed higher levels of IL-1β release from THP-1 cells and RAW264.7 when live S. aureus was used in an in vitro infection assay." (PMID 33322651, 2020). "Together, our data demonstrate that Mtb induces potassium efflux-driven activation of the canonical NLRP3 inflammasome upon infection of human monocytes and macrophages, followed by GSDMD-dependent pyroptotic cell death with release of IL-1β." (PMID 32385301, 2020). "As expected, mice infected with Cr had increased colonic tissue expression of several cytokines associated with a pro-inflammatory Th1/Th17 immune response including IL-17A, IL-22, IL-6, IL-1β, TNF-α, and IFN-γ on day 12 after infection." (PMID 33076301, 2020). "Despite similar infection rates, sh-MG53 cells yielded increased IFNβ and IL-1β secretion after SeV infection compared to sh-control cells." (PMID 32681036, 2020). "We subsequently analyzed the kinetics of the most intensive pro-inflammatory cytokines including TNF-α, IL-1β, IL-6, and IL-18 in sera of pigs upon SY18 infection." (PMID 33553280, 2020). "ELISA results revealed that M. bovis infection induced the secretion of IL-1β, IL-10, and TNF-α after 24 h of infection in THP-1 cells." (PMID 32265874, 2020). "IL-1β levels were only significantly increased following “PAO1-alone” and after “IAV+PAO1” infections." (PMID 32117268, 2020). "SS2 induced significantly more IL-1β and cytotoxicity compared with the ∆ SLY strain 16 h post infection." (PMID 32922370, 2020). "The difference is that, on day 0 post-infection, intraperitoneal injection of CoA can obviously induce the expressions of TNF-α, IL-1β, IL-6, and IFN-γ in the lungs, but oral administration of valine only stimulates IFN-γ." (PMID 32345342, 2020).
infection (continued). "Of these genes, SAA2 was the most significant (-10logp-value of 81); the distinctive genes in the SARS-CoV-2’s infection response were CSF3, CSF2, IL1B, and PTGS2." (PMID 33301474, 2020). "To validate IL-1β effects in vivo, we orally infected WT and IL-1R1-/- mice with CA and examined Foxp3+ cells in MOIL three days after infection and in vitro restimulation." (PMID 33240286, 2020). "The levels of IL-1β, IL-6, and TNF-α were initially detected at 4 h after infection and gradually increased in a time-dependent manner." (PMID 32433516, 2020). "After infection of J774 cells with S. suis, a large number of TNF-α and IL-1β were produced, indicating that S. suis triggered a severe inflammatory response in cells." (PMID 33329477, 2020). "IL-1β, COX-2, and IL-8 levels in the presence of each P. gulae strain were highest at 2 h after infection; these levels were significantly higher than those in uninfected cells (P < 0.001)." (PMID 32080231, 2020). "Based on these data, IL-6, IL-1β, and TNF-α elevation during fetal infection stimulates LRG expression in fetal hepatocytes to increase the umbilical cord serum LRG levels." (PMID 33211747, 2020). "CXCL2 (MIP‐2) and CXCL1 (KC), which are responsible for the infiltration of neutrophils and monocytes, were suppressed at the beginning of infection (6 h), whereas inhibition of CCL2 (MCP‐1), TNF‐α, IL‐6, IL‐1β and IL‐17A appeared after 24 h." (PMID 33014369, 2020). "Using Luminex multiplex immunoassay, we measured cell culture supernatant fluid levels of the cytokines TNF-α, IL-1β, IL-6, IL-10, RANTES, and IL-8 at 6 h and 24 h following infection." (PMID 32994292, 2020). "To determine if CFTR KO alters macrophage cytokine production, we measured production of 5 cytokines (IL-8, IL-1β, IL-6, IL-10, and TNF-α) at baseline and in response to infection with B. cenocepacia." (PMID 32973772, 2020). "The mRNA levels of IL1β, IL6, TNF-α and IFN-β in porcine intestinal epithelial cells infected with SDSX16-P10 strain were much lower than SDSX16-P75 at 18 h post-infection (hpi)." (PMID 32244640, 2020). "M2 localises to the Golgi upon infection, leading to the acidification of the Golgi compartment, which activates NLRP3 inflammasome and IL-1β production." (PMID 32709018, 2020). "Pharmacological inhibition of IL-1β as well as its converting enzyme (ICE), which is essential for the release of IL-1β, has allowed to reduce memory impaiments induced by infection or stress in aged mice and has improved the performance of aged rats." (PMID 32121189, 2020). "Levels of IL-1β, IL-6, CCL2, CCL3, CXCL1, and CXCL2 were significantly greater 6 h following infection than in mock-infected mice (P < 0.05) but were similar among wild-type, CCR2−/−, and Nr4a1−/− mice." (PMID 31818962, 2020). "Based on the pneumococcal serotypes used for the infection, the NLRP3-dependent IL-1β secretion by human cells varies." (PMID 33424869, 2020). "infection, whereas the corresponding early responding genes in SCC cells were IL10, IL1β, IL1α, TNF, CXCL10, CXCL1, HBEGF, IL6, and CSF3." (PMID 31912662, 2020). "For that purpose, WT BMDMs were infected with tachyzoites at multiplicity of infection (MOI; cell:parasite ratio) of 0.5 and IL-1β production was measured in different times of infection (3, 6, and 18 h)." (PMID 32523898, 2020). "In contrast, the attenuated NH/P68 presented a higher sensitivity to classical and IFN-α activation, and infection resulted in downregulated expression of MHC class I in all the subsets and release of IL-1α, IL-1β, and IL-18 from moM1." (PMID 32178332, 2020). "Collectively, these findings demonstrate that the host mounts an initial immune response to S. aureus craniotomy infection that is TLR2- and caspase-1-dependent, with IL-1β being a key player." (PMID 32290861, 2020).
infection (continued). "The mRNA expression of the pro-inflammatory cytokines IL-1β, IL-8, and TNF-α, as well as the anti-inflammatory cytokine IL-10 were quantified by qRT-PCR after infection of THP-1 macrophages with the various mycobacteria for 18 h." (PMID 32117140, 2020). "A majority (64/92) of NF-κB signaling pathway genes were downregulated more than 2-fold with infection, whereas only 5 of 92 were upregulated, BCL2A1, IL1B, CXCL8, MMP9, and SOD2." (PMID 33194960, 2020). "Thus, increased IL-1β production may be important in infection control." (PMID 32266161, 2020). "In the study, after infection, the levels of TNF-α, IL-6, and IL-1β in obese mice increased for a short time, and then decreased, which is conducive to reducing the inflammatory immune damage of the spleen and promoting the repair effect." (PMID 32104715, 2020). "It has been reported that IL-1β and TNF-α play critical roles in the host defense against infection and are responsible for early inflammatory responses." (PMID 32746898, 2020). "Upon infection, TNF-α, IL-4, and IL-6 expressions heightened, while IL-3 and IL-1β only appeared in trace amounts." (PMID 32943637, 2020). "Other pro inflammatory cytokines, IL-1β and TNF-α were similarly increased in the colon after infection of Camp+/+ and Camp−/- mice." (PMID 32658599, 2020). "After infection with MGAS5005, MGAS315, or MGAS6180, the levels of three such cytokines (IFN-γ, TNF-α, and IL-1β), which are important for effective innate immunity against GAS, increased in SseM1-immunized mice compared with control mice." (PMID 32308652, 2020). "It has even been suggested that in vitro infection of human neutrophils leads to evasion of NLRP3 activation and IL-1β secretion." (PMID 32753607, 2020). "The levels of IL-1β, IL-6, and TNF-α in serum and lung samples were compared between innate immune effector depleted mice and control mice 24 h after infection." (PMID 33163539, 2020). "The first, 5 days of infection showed peak levels of IL-1RA, MCP-1, MIP-1β and TNF-α; the second 5 days had peak levels of GM-CSF, IL-1β, IL-6, IL-8, IL-9, IP-10 and MIP-1α; VEGF peaked at 11–15 days." (PMID 32264832, 2020). "The large increase in serum IL-1β, in the ABX-fed group is possibly indicative of a subclinical infection in that group." (PMID 32190298, 2020). "The release of select inflammatory proteins (IL6, IL8, CSF3, IL1β, CXCL10, and ICAM1) into the culture medium of HEKs and SCC cells following infection with C. t." (PMID 31912662, 2020). "Presently, the induction level of IL-1β, CXCL1 (KC), CXCL2 (MIP-2), and CCL2 (MCP-1) mRNA in the lungs after infection was significantly higher in klotho KO mice than in klotho WT mice." (PMID 33329595, 2020). "Here, we show that CaSR upregulation after infection in TM in a rat model of UPEC induces the activation of the NLRP3 inflammasome pathway and thereby enhances IL-1β secretion and reduces the testosterone level in the blood." (PMID 33193351, 2020). "Both type-I and type-II strains induced the upregulated expression of pro-IL-1β, but secreted very little mature IL-1β in THP1 monocytes after infection." (PMID 32230726, 2020). "Infection of MDMs with HIV-1 in vitro results in the upregulation and constitutive secretion of IL-1β in culture supernatants." (PMID 32994328, 2020). "IL-1β, IL-12, and TNF levels in the TNF-/- mice showed significant decreases compared with those of the controls TNFf/f and BTNF-/- mice at 3 weeks after infection." (PMID 32742607, 2020). "In general, H3N2 and H5N1 infection induced IFN-α, TNF-α, MCP-1 (CCL-2), IL-1β, and IL-6 responses in ANP32B+/+ mice were reduced in ANP32B−/− mice, particularly 3 days post infection." (PMID 32231671, 2020). "We measured the protein levels of NF-kB, RAGE, TNFα, and IL-1β in lung tissue and we found that positive expression levels were induced by the A/H5N1 lethal infection (mock-treated groups)." (PMID 33176722, 2020).
infection (continued). "The infection of human AMs by the RSV stimulates the secretion of several proinflammatory cytokines, including IL-6, TNF-α, IL-1β, and IL-8." (PMID 32660087, 2020). "Similar to the mRNA analysis, expression levels of IL-1β, COX-2, and IL-8 induced by strain D049 (type C) infection were significantly higher than expression levels induced by strains ATCC 51700 (type A) or D040 (type B)." (PMID 32080231, 2020). "The present study also showed a significant up-regulation in the expression of IL-1β and TNF-α mRNA following infection with L. major compared with the control group." (PMID 33252120, 2020). "VVΔTK∆N1L infection upregulates the expression of the IL1 family of cytokines from both DCs and macrophages: IL1α, IL1β and IL18." (PMID 32217766, 2020). "After 2 h of infection with Mtb WT, there was a significant upregulation of immune modulators such as TNF, IL-1A, IL-1B and IL-6." (PMID 32938685, 2020). "The effector caspase-1 cleaves interleukin (IL)-1β, IL-18, and gasdermin D (GSDMD), resulting in cytokine release and the induction of pyroptotic cell death to eliminate infections and restore homeostasis." (PMID 32962268, 2020). "ASC specs were found in the plasma of HIV positive patients, and infection with HIV stimulated the NLRP3 inflammasome in monocytes as well as production of caspase-1, IL-1β and IL-18 in brain microglial cells." (PMID 32066471, 2020). "Our results show that the relative transcription levels of IL-17A, IL-22, IL-6, IL-1β, IFN-γ, and TNF-α increased at 5 and 12 days post H9N2 AIV infection, and these results are consistent with our previous research results and other reports." (PMID 33294434, 2020). "Ms_YrbE3A infection resulted in the highest concentrations of pro-inflammatory cytokines, including TNF-α, IL-1β, IL-6, MCP-1, IL-1α, IL-12p70, and IFN-γ, in the lungs at 2 d PI and later decreasing rapidly from 4 to 21 d PI." (PMID 32316659, 2020). "At 2 weeks post infection, TNF-α and IL-1β levels were much lower compared to 1-week post infection." (PMID 32958779, 2020). "At lower doses of infection, SPN:Ply-H elicited reduced secretion of TNF-α, IL-1β and IL-12 compared to SPNΔply." (PMID 33216805, 2020). "Changes in gene expression in the brains of infected animals is minimal at 2- and 4-days post infection with moderate increases in Interferon-inducible CXCL10, CXCL11, B2m, and STAT1, as well as pro-inflammatory TNF, IL-1b and C3." (PMID 32133008, 2020). "Real time qPCR analysis of major pro‐inflammatory cytokines including IL‐1β, TNF‐α, and IL‐6 showed a less severe inflammatory response in the LL‐37‐Lung after infection." (PMID 31782624, 2020). "Third, markers of inflammation, including neutrophil infiltration and the production of proinflammatory cytokines, such as TNF-α, IL-1β and IL-6, production in the BALF were determined 24 h post-infection." (PMID 32197534, 2020). "As expected, a significant increase of IL-1β was detected in the supernatant of DENV-2-infected cells at 36 and 48 h post-infection, in contrast with mock-infected cell supernatant." (PMID 32210961, 2020). "Even when a multiplicity of infection (MOI) of 10 was used, the secretion of IL-1β was still low, whereas that of TNF increased, showing that the macrophages were upregulating their response to infection with higher doses of M. tuberculosis 6C4." (PMID 32327653, 2020). "After overexpression of NLRP3 and infection with GM, IL-1β expression increased from 107.5 pg/mL to 169.3 pg/mL, and after inhibition of NLRP3 with Si-RNA, the expression of IL-1β decreased from 152.8 pg/mL to 87.0 pg/mL." (PMID 32293543, 2020). "Proinflammatory IL-1β, IL-6, and tumor necrosis factor alpha (TNF-α) levels were markedly increased upon any infection compared to mock control and were higher during C. glabrata or C. parapsilosis infections." (PMID 33024045, 2020).
infection (continued). "Compared with the CK group, IL-6, IL-1β, TNF-α and IL-17 all increased in the MC group under the infection of E. coli O157, while the GOS group reversed this increase under intervention." (PMID 33233359, 2020). "Mice treated with antibodies against IL-1β and TNF-α, or with inhibitor of inducible NO synthase (iNOS), showed a reduced incidence of VID upon infection with a low dose of EMCV-D." (PMID 32727064, 2020). "Two days after infection (day 2), the levels of pro-inflammatory cytokines IL-6, TNF-α, and IL-1β were significantly higher in the group ZE compared with the group ST." (PMID 32486242, 2020). "Recent study demonstrated that LPS promoted the production of IL-1β and TNF-α in response to infection mediated by a mechanism for A2AR targeting in microglia." (PMID 32028987, 2020). "Seven cytokines were identified as infection-specific, showing elevated concentrations in the septic TKR cohort compared to both the aseptic TKR and primary TKA cohorts: IL-1α, IL-1β, IL-6, IL-8, MCP-1, MIP-1α, and MIP-1β (p < 0.05)." (PMID 32867801, 2020). "In infection-induced preterm birth, the number of macrophages is increased in the decidua, and macrophages secrete proinflammatory cytokines such as TNF-α and IL-1β." (PMID 33036475, 2020). "In these diseases, NF-κB occurs largely in response to cytokines such as IL-1β and TNF-α or by infection with viruses during exacerbations." (PMID 32038638, 2019). "In contrast, infection of J774 cells by Pseudomonas aeruginosa PAO1 (positive control) led to high levels of secretion of both KC and IL-1β." (PMID 31641083, 2019). "In contrast, infection of SK-N-SH with WNV reportedly results in a sharp increase of key pro-inflammatory cytokines (e.g., IL-1β, IL-6, IL-8, and TNF-α) at day 2 p.i., which coincides with peak virus replication." (PMID 31699097, 2019). "Infection of primed BMDMs with increased MOI of VSV or EMCV led to increased caspase-1 maturation, IL-1β production, and cell death." (PMID 31024004, 2019). "Experiments in caspase-11-deficient primary macrophages showed that caspase-11 did not contribute to MNV-induced caspase-1 activation and that the latter was sufficient for mediating IL-1β maturation and secretion upon MNV infection." (PMID 31017981, 2019). "After high-dose infection (5 × 106 CFU per mouse), bronchoalveolar lavage fluid (BALF) TNF levels recovered at 2 h and IL-1β and IL-6 at 4 h were higher in response to the TIGR4 strain compared to infection with the TIGR4 Δcps strain." (PMID 31551336, 2019). "After infection, when compared with the lean group, the contents of TNF-α, IL-1β, IL-6, IL-8, resistin, and leptin in the lean-E." (PMID 31085802, 2019). "Following infection, pNECs showed measurable quantities of interferon (IFN)-λ, IL-1β, IL-8, IP-10 and MIP1-α." (PMID 31747925, 2019). "As expected, several cytokines including TNF-α, IL-1β, IL-6, IL-8, and IFN-γ were significantly increased in a time-dependent manner upon virulent Mtb strain H37Rv infection detected by qRT-PCR in hMDMs." (PMID 30717477, 2019). "Mechanistically, ingenuity pathway analyses revealed a tilt in the anti‐inflammatory IL‐10 versus pro‐inflammatory IL‐1β and IL‐18 balance during CHIKV nsP‐mutant infection that modified acute antiviral and cell signaling canonical pathways." (PMID 31015278, 2019). "Nevertheless, the levels of IL-1β, IL-6, and TNF-α in the HAdV-7 group were higher than the HAdV-3 group post 3, 5, and 7 days of infection (p < 0.01)." (PMID 30626350, 2019). "The blood of infected animals was collected 5–40 days after the infection for the evaluation of plasmatic levels of TNF-α and IL-1β over the course of the disease." (PMID 31138231, 2019). "In the CNS of WT mice, increased IFN-α1, IFN-β, TNF, IL-1α, IL-1β, IL-6, and IFN-γ mRNA levels were seen at day 4 post infection, and with the exception of IFN-α1, which decreased slightly, cytokine mRNA levels increased further by day 6 post infection." (PMID 31511023, 2019).